TNF (tumor necrosis factor)
Diseases named in the same sentence as TNF in open-access papers (continued):
Sharing a sentence is not in itself a finding about the gene and the disease.
asthma (continued). "TNF-α inhibitors, such as etanercept, are not effective in patients suffering from neutrophil-based asthma because they are not sensitive to glucocorticoids." (PMID 29359169, 2017). "Neutralizing TNF-α improves AHR and airway obstruction in severe asthma." (PMID 29359169, 2017). "In addition, in asthma patients with a high BMI, NPY level was positively correlated with adiponectin and TNF-α." (PMID 28128231, 2017). "In asthma, GAC1 inhibits TNF-α secretion through the NF-κB pathway." (PMID 29344411, 2017). "The effects of ALOX5 rs892690 on ever asthma, LT-α rs2844484 and TNF-α rs1800629 on bronchitis were not considered significant with the adjusted thresholds, while the others remained significant after the correction." (PMID 28740106, 2017). "A similar pathway has been described for TNF-α-high-asthma, which has been known to be severe and non-responsive to asthma medications." (PMID 28609485, 2017). "When comparing the effectiveness of the two periodontal treatments in the mice without asthma, we noticed that the conventional treatment decreased the macrophages, as well as IL-6 and TNF-α, corroborating with the literature." (PMID 29145431, 2017). "After treating with prednisone or HFBP, IL-4 and TNF-α level significantly reduced (P < 0.05), suggesting that HFBP could inhibit IL-4 and TNF-α expression in the blood of asthma mice." (PMID 27143988, 2016). "Like our study, a previous study reported that there is no elevation of TNFα or GM-CSF in BAL fluids from the subjects of asthma." (PMID 26011707, 2015). "Based on our results, CCL2, CXCL12, and IL8 may have correlated mRNA and protein secretion levels that differ between fatal asthma- and non-asthma-derived ASM, but the difference in IL8 may only be noticeable with TNFα induction due to its low baseline levels." (PMID 26207385, 2015). "Therefore, the aim of the study was to assess the amount and activity of MMP-9 in context of pro-inflammatory cytokines (IL-6, IL-8 and tumor necrosis factor, TNF), measured in EBC of asthma-suffering children, treated with inhaled steroids." (PMID 25650123, 2015). "TNF/EBC levels were similar in both, asthma and healthy children." (PMID 25650123, 2015). "In summary, HDAC2 gene expression and enzyme activity might be suppressed in patientswith asthma, resulting in NF-κB activation and increased BAL levels of IL-8, IL-5,IL-13, GM-CSF, and TNF-α." (PMID 25923460, 2015). "A lower TNFα methylation percentage was found in children with asthma (mean ± SD: 31.53 ± 25.96%) in contrast to children without (41.14 ± 26.88%, P = 0.018)." (PMID 25960783, 2015). "Thus, TNF-a appears to participate to the mechanism of airways neutrophilic inflammation in COPD and severe asthma." (PMID 25371053, 2014). "Cytokines such as TNFα, IL6 secreted by the adipocytes are important mediators of asthma." (PMID 24409194, 2014). "Given the finding that TNF-α levels are up-regulated in severe refractory asthma and COPD, it is tempting to speculate that TNF-α might regulate the longevity of eosinophils as a possible pathogenic mechanism." (PMID 24587316, 2014). "A total of 2,743 children had complete data on asthma, wheeze, potential confounders, NO2, ozone, PM2.5, PM2.5 absorbance, and at least one SNP of interest (n = 2,367 with GSTP1 rs1138272; n = 2,559 with GSTP1 rs1695; n = 2,318 with TNF rs1800629)." (PMID 24465030, 2014). "In asthma, epithelial shedding is largely attributed to the induction of apoptosis in AECs by infiltrating T cells and eosinophils along with increased pro-inflammatory cytokines including IFN-gamma and TNF-alpha." (PMID 25324978, 2014). "Likewise, tumor necrosis factor-alpha (TNF-α) is considered to be a significant proinflammation and the promoter of the airway inflammation in asthma." (PMID 25101137, 2014). "Dexamethasone fails to abolish TNF-α-induced IL-33 upregulation in airway smooth muscle cells, which are a major source of IL-33 in asthma." (PMID 24822215, 2014).
asthma (continued). "In addition to CCL11/eotaixn-1 and TNF-alpha, HBEC exposed to TSLP induced the secretion of CCL22/MDC and CCL17/TARC, two CCR4-ligands that are considered critical Th2-related chemokines in asthma exacerbations." (PMID 25546419, 2014). "Before the advent of genome-wide association studies (GWAS), ADAM33, ADRB2, CD14, MS4A2 (alias FCER1B), IL13, IL4, IL4R, and TNF constituted the most replicated non-HLA candidate genes with asthma and related traits." (PMID 24039878, 2013). "Here, we use primary AEC cultures stimulated with TNFα and interferon γ (IFNγ) to determine whether dysregulation of XIAP, cIAP1, and cIAP2 contributes to apoptosis observed in asthma-related inflammation." (PMID 24303189, 2013). "On the other hand, targeting TNF-α in severe asthma with golimumab yields responders and non-responders." (PMID 24032029, 2013). "There are limitations in the sensitivity and specificity of hsCRP, TNF-α, and WBC in judging whether patients with asthma are also suffering from bacterial infection." (PMID 24341820, 2013). "TNF-α and IFN-γ upregulate CCR1 expression by ASMC, so binding of CCL15 to CCR1 might contribute to the severity and pesistence of asthma." (PMID 23258953, 2012). "Inflammatory (TNF-α) and growth factors (TGF, bFGF, and PDGF) that are usually released during inflammation in chronic airway diseases, such as asthma and COPD, have a mitogenic effect and they may be implicated in airway remodelling." (PMID 24049651, 2012). "In summary, administration of SCTE in this mouse asthma model significantly decreased the number of eosinophils in BALF and lung tissue, and reduced IL-4 IL-5, IL-13, TNF-α, and eotaxin production in BALF and total IgE and OVA-specific IgE levels in plasma after OVA challenge." (PMID 23244755, 2012). "In the GCE-induced asthma model, intranasal administration of GCE increased airway hyperresponsiveness (AHR), inflammatory cell infiltration, productions of serum immunoglobulin E, interleukin (IL)-5, IL-13 and TNF-α production in alveolar macrophages." (PMID 23094102, 2012). "In this study, we hypothesized that PAR-2 activation of the alveolar macrophages and production of pro-inflammatory components, such as TNF-α, play a critical role in the GCE-induced asthma model." (PMID 23094102, 2012). "The purpose of this study was to define the role of oxytocin in modulating human airway smooth muscle (HASMCs) function in the presence and absence of IL-13 and TNFα, cytokines known to be important in asthma." (PMID 20670427, 2010). "Immunomodulating drugs such as inhibitors of tumor necrosis factor-α (etanercept) and intravenous immunoglobulins have been used in treating refractory asthma; however, no consistent improvement in lung function has been demonstrated." (PMID 20181197, 2009). "The expression of TNF-α and TGF-β1 are elevated in lung and bronchoalveolar lavage fluid in asthma." (PMID 16359550, 2005). "Fructus Xanthii exerts anti-asthmatic effects by modulating HSP90AB1/IL6/TNF and PI3K-AKT pathways, regulating inflammation, cell cycle, apoptosis, and immune homeostasis, providing empirical support for multi-target traditional Chinese medicine strategies in asthma management." (PMID 41403444, 2025). "The rapid and effective response to TNF-α blockade therapy further supported the “Type-2-low” classification, indicating that TNF-α inhibition could be a viable therapeutic option for refractory EGPA in patients with a history of “Type-2-low” asthma." (PMID 40703351, 2025). "However, probiotics did not significantly affect daytime or nighttime asthma symptom scores, forced expiratory volume in 1 s, forced vital capacity, peak expiratory flow, or tumor necrosis factor-α levels (P ≥ 0.05)." (PMID 41561940, 2025).
asthma (continued). "Conversely, nonallergic asthma, affecting 10–40% of asthma cases, is characterized by an acute inflammatory response involving cytokines such as IL-1, IL-6, IL-8, and TNF-α, leading to neutrophil infiltration and airway inflammation." (PMID 40410722, 2025). "Biologics targeting IFN-γ, TNF-α, and IL-33 are not yet available for asthma and COPD patients." (PMID 39439801, 2024). "Subsequent exploration demonstrated a significant increase in Th2 cell population in the lungs of Cc10−/− mouse asthma model, indicating that CC10 might regulate Th2 cell differentiation and immune responses by suppressing IL-6 and TNF-α secretion from lung DCs." (PMID 39078462, 2024). "Asthmatic mice with and without fluconazole exhibited retardation of weight gain, increased IgE and IL-4 in serum, increased serum IL-6 but not serum TNF-α (increased serum IL-10 only in asthma with fluconazole), and prominent IL-4 and IgE in the lung homogenates." (PMID 39484217, 2024). "The serum levels of TNF‐α (p = 0.025), IFN‐γ (p = 0.011), CCL22 (p = 0.022), IL‐12p70 (p = 0.021), CXCL10 (p = 0.028), CCL2 (p = 0.028), CCL13 (p = 0.024), IL‐4 (p = 0.026), IL‐13 (p = 0.024), and CCL11 (p = 0.028) were found to be downregulated in stable asthma when compared to acute asthma." (PMID 39508721, 2024). "Additionally, loratadine, when combined with montelukast, resulted in a reduction in IL-4 and TNF-α without increasing adverse effects in children with asthma." (PMID 38794179, 2024). "The levels of interferon‐γ (IFN‐γ), tumor necrosis factor‐a (TNF‐α), chemokine CCL22 (CCL22), interleukin 12 (IL‐12), chemokine CCL4 (CCL4), chemokine CCL2 (CCL2), and chemokine CCL13 (CCL13)were significantly higher in the acute asthma group than in the stable asthma group." (PMID 39508721, 2024). "Consequently, airway epithelium in patients with T2 asthma overproduces a broad pallet of pro-inflammatory cytokines and mediators including alarmins (IL-25, IL-33, TSLP), as well as IL-6, IL-8, IL-1α/β, RANTES, or TNF in response to environmental triggers." (PMID 37199256, 2023). "Airway epithelial cells can be activated by cytokines (IL-1β, IFN-γ,TNF-α, etc.)or PAMPS (Pathogen-related molecular patterns) via the TLRs-NF-κb pathway and releases CCL13, which recruits eosinophils and promotes the polarization of M2 macrophages to mediate the progression of asthma." (PMID 37153575, 2023). "Whether TNFα has a similar role in lung fibroblasts and whether asthma dysregulates the ER stress/UPR pathway in these cells is not known." (PMID 36760534, 2023). "However, OS biomarkers NO2−, lipid peroxide, protein sulfhydrils, and inflammatory biomarkers TNFα, IL-4, IL-37, IL-1β, IL-1RL1, IL-1R1, NLRP3, and TGF-β1 showed positive association with asthma in nonsmokers, but not in smokers." (PMID 37367073, 2023). "The transcriptomic analysis also revealed that combined exposure to TNF-α and IFN-γ affects several gene expressions, which impairs corticosteroid sensitivity in ASM and may lead to persistent symptoms and worsening of severe pediatric asthma." (PMID 37377958, 2023). "In addition, chemokine production by TNF-α and IFN-γ has been shown to be insensitive to GCs via multiple mechanisms, thus representing a unique cellular model to dissect the mechanisms of GC insensitivity in asthma, or find new strategies to reverse it." (PMID 37299150, 2023). "Severe asthma refractory to biologic agents seems likely to be sustained by a significant slice of T2-low inflammation characterized by different T-cell effectors (T-helper 1 and T-helper 17) and specific cytokines (IL-17, IL-6, IL-8, interferon (IFN) and tumor necrosis factor (TNF))." (PMID 37189844, 2023). "TNFα, lung fibroblasts, and TSLP form an important axis to promote type 2 immune responses in asthmatic lungs that may contribute to the chronic inflammation in asthma." (PMID 36760534, 2023).
asthma (continued). "Various cytokines, including TNF-α, transforming growth factor-β (TGF-β), IL-1β, and platelet-derived growth factor (PDGF-BB), have been found to be important mediators of airway remodeling and fibrotic responses, and they can also initiate and drive the inflammatory response in asthma." (PMID 35172671, 2022). "TNFα has a potent effect on human ASM by inducing the production of pro-inflammatory mediators, extracellular matrix deposition and remodeling, and enhancing intracellular Ca2+ ([Ca2+]i) regulatory mechanisms that promote pathological and functional features in asthma." (PMID 35578269, 2022). "Interestingly, clinical trials with either anti-TNF-α strategies or blocking the IL-17RA receptor did not adequately control severe asthma." (PMID 36517803, 2022). "Moreover, the excessive synthesis by the adipose tissue of pro-inflammatory cytokines, such as IL-1β, IL-6, TNF-α, and TGF-β, may contribute to asthma pathogenesis." (PMID 35807067, 2022). "However, TNF-α and MAPK inhibitors are not suitable for asthma treatment due to numerous adverse effects associated with long-term use." (PMID 35600871, 2022). "Moreover, blocking the TL1A/DR3 axis may be a novel therapeutic approach for asthma, because it inhibits the inflammatory response and improves EMT established by TNF-a." (PMID 35359966, 2022). "TNF-α is a pleiotropic proinflammatory cytokine, which promotes airway hyper-responsiveness, mucus production, various inflammatory cell activation, and phenotypes of asthma, and some studies showed that TNF-α as a target for asthma treatment has significant efficacy in clinical trials." (PMID 35815290, 2022). "Compared with the model group, Danlong Dingchuan Decoction effectively reduced the expression levels of TNF-α, IL-4, TGF-β1, IL-6, IL-8, and IL-1β in the lung tissue, reduced the release of inflammatory factors, alleviated airway inflammatory response, and relieved asthma symptoms." (PMID 35186104, 2022). "Subsequently, the OVA-induced asthma mice were treated with M2Φ-Exos, and we found a significant inhibition in fibrosis and cell apoptosis in mouse lung tissues, a reduction in the number of granulocytes, and a decline in the secretion of OVA-induced IL-1β, IL-6, TNF-α, and MCP-1." (PMID 33994863, 2021). "Since TNF alpha is localized to human mast cells, this creates the possibility for MMP-3 to act potentially as an activator of TNF alpha release, thereby enhancing the profibrotic course and influencing endothelial cell activation and the recruitment of infiltrating leucocytes in asthma." (PMID 33920429, 2021). "In addition, enrichment analysis suggested that the therapeutic mechanism of SZ in treating asthma might involve signaling pathways of PI3K-Akt, TNF, and hypoxia inducible factor-1." (PMID 33505505, 2021). "The tumor necrosis factor (TNF), Toll-like receptor (TLR), and Th17 cell differentiation-related, nucleotide-binding oligomerization domain (NOD)-like receptor, and NF-kappaB pathways were identified as the most significant signaling pathways involved in the therapeutic effect of ACG on asthma." (PMID 33645621, 2021). "Enriched KEGG pathways could be strongly related to inflammatory processes and regulation in the mixed-cell analysis (with TNF and the HLA, human leukocyte antigen, loci HLA-DRA and HLA-DOB largely contributing to this finding), including the KEGG pathway “Asthma”." (PMID 33076907, 2020). "Interestingly, TSLP expression in moDCs from triple co-culture correlated positively with IL12p40, IL-6, and TNF-α in asthma, whereas in COPD with CHI3L1, IL12p40, IL-6, IL-8, TNF-α, and IL-1β suggesting a different pathway of immune response in asthma and COPD." (PMID 32842623, 2020). "Collectively, these data suggest that Nec‐1 can antagonize TNF‐α‐induced necroptosis in 16HBE cells with MUC1 downregulation and thus, furtherly support that MUC1 as a novel protective molecule in cell necroptosis on asthma through mediating the p‐RIPK1‐s166 expression." (PMID 30666647, 2019).
asthma (continued). "Increased levels of TNFα were related to many pulmonary inflammatory diseases including chronic obstructive pulmonary disease (COPD), acute respiratory distress syndrome (ARDS), acute lung injury (ALI), sarcoidosis, asthma and interstitial pulmonary fibrosis (IPF)." (PMID 31780733, 2019). "However, it is not easy to induce BEAS-2B cells to express eotaxin using TNF-α, and previous experiments showed that TNF/IL-4 could stimulate BEAS-2B cells to express eotaxin, which attracted eosinophils into allergic airways and lung tissue in asthma." (PMID 29962952, 2018). "In this study, the levels of miR-1 and the Th1-expressed cytokine IFN-γ in peripheral blood of children with acute-stage asthma were significantly lower, whereas the expression levels of the Th2 cytokines IL-4, IL-5, IL-8, and TNF-α were significantly higher than levels in children without asthma." (PMID 30046607, 2018). "Nevertheless, the studies on TNF-alpha inhibitors should not be abandoned, given the significant and not yet fully understood heterogeneity of asthma that does not allow us, at the moment, to identify which phenotype could possibly benefit from these drugs." (PMID 25671117, 2015). "However, a large study carried out in patients with persistent severe asthma receiving golimumab, a human anti-TNF-α monoclonal antibody, did not evidence any significant improvement in lung function and disease exacerbations." (PMID 25878402, 2015). "In addition, a mediation analysis demonstrated that TNFα 5′CGI may be a potential epigenetic link between phthalate and asthma." (PMID 25960783, 2015). "In addition, to estimate whether TNFα 5′CGI methylation is an intervening variable between 5OH-MEHP and asthma, we conducted a mediation analysis." (PMID 25960783, 2015). "Interestingly CXCL10 production induced by IFNγ or cytomix is also not inhibited by current asthma therapies such as fluticasone and/or salmeterol, whereas IL-1β- and TNF-α-induced release is markedly reduced by these agents." (PMID 24648846, 2014). "Since TNF-alpha heightens the development of airway TSLP/Th2 pro-asthmatic responses after dsRNA exposure, our findings suggests that TNF-alpha may amplify the potential effect of TSLP in viral-induced asthma exacerbations." (PMID 25546419, 2014). "In the present study, the serum leptin and TNF-α levels were higher in obese individuals, irrespective of the presence of asthma, suggesting that leptin might be involved in the priming of circulating eosinophils." (PMID 23773659, 2013). "However, a larger study carried out in patients with persistent severe asthma receiving golimumab, another TNF-α blocking antibody, did not detect any significant improvement in lung function and disease exacerbations." (PMID 23853765, 2013). "Type 1 cytokines such as TNF-α, IL-12 and IFN-γ have a pivotal role in enhancing the infiltration and activation of effector cells in host defence and many inflammatory diseases, and may also play an important role in asthma pathogenesis." (PMID 23043798, 2012). "Furthermore, additional inflammatory cytokines such as IL-1β and TNF-α are derived primarily from macrophages (not Th1 or Th2-derived) and also play a significant role in asthma inflammation." (PMID 19152703, 2009). "In addition, cytokines secreted by type 1 lymphocytes (Th1) and macrophages, including IL-1β, TNF-α, and IFN-γ, may be increased in asthma subjects and contribute to the inflammatory process." (PMID 19152703, 2009). "In this context, the present findings suggest, indirectly, that beneficial effects of anti-TNFα drugs in refractory asthma may reflect anti-neutrophil rather than anti-eosinophil effects." (PMID 18234086, 2008). "The upregulation of TNF-α and IL-13 suggests that these cytokines may play a key role in mediating this process and highlights the importance of these cytokines as therapeutic targets for RSV induced asthma." (PMID 16893457, 2006).